CLDN1 (claudin 1)
Diseases named in the same sentence as CLDN1 in open-access papers (continued):
Sharing a sentence is not in itself a finding about the gene and the disease.
tumor (continued). "Strikingly, the abnormal localization of CLDN1 and OCLN that we documented following TACSTD2 silencing both in hepatoma cell lines and in primary human hepatocytes was analogous to that observed in tumor tissue of patients with HCV-associated HCC." (PMID 29538454, 2018). "However, clinical evidence has indicated that CLDN1 is a poor prognostic marker because higher CLDN1 levels are present in tumor tissues from distant metastatic sites in patients than in matched primary tumors." (PMID 28757546, 2017). "CLDN1 serves as an oncogene or a tumor suppressor in a tissue-specific manner." (PMID 29169318, 2017). "Finally, our research showed that Claudin 1, Claudin 4, and Claudin 7 were closely related to tumour growth and metastasis." (PMID 28376864, 2017). "Our anti-CLDN1 mAb, by affecting tumor cell migration, could play an important role in the control of cancer cell invasiveness." (PMID 28659146, 2017). "CLDN1 membrane overexpression in all tested primary tumor samples from patients with mCRC supports the hypothesis that CLDN1 could represent a target for antibody-based therapy." (PMID 28659146, 2017). "In addition, duplicate immunofluorescent staining revealed co-localization of Nm23H1 and CLDN1 in the same primary tumor." (PMID 27376780, 2016). "H scores: % claudin 1 positive tumor cells multiplied by the intensity of staining (scale 1–3)." (PMID 27649506, 2016). "Claudin 1 plays a key role in facilitating the collective migration of tumor cells." (PMID 26633531, 2015). "Moreover, we also showed that there was a positive relationship between high claudin 1 protein levels in the tumor and patient age." (PMID 26633531, 2015). "In addition, H&E staining of tumors showed that NC tumor cells arranged more closely than CLDN1-KD cells." (PMID 25544763, 2015). "However, overexpression of CLDN1 in a luminal B subtype MDA-MB361 cells, which are positive for ER, PR and Her2, leads to cell apoptosis in 3D tumor spheroid cultures, inconsistent with the finding of the antiapoptotic effect of CLDN1 in MCF7 cell lines." (PMID 26067567, 2015). "It has been previously suggested that CLAUDIN 1 acts as a tumor suppressor." (PMID 24946763, 2014). "In particular claudin-1 is implicated as an active player in EMT and tumor progression." (PMID 25278811, 2014). "Decreased claudin 1 and claudin 10 expression may lead to the compromised tight Junctions’ function and the neoplasia progression." (PMID 23591077, 2013). "Decreased expressions of claudin 1 and claudin 10 might lead to the compromised tight Junctions’ function and, thus, neoplasia progression was easy to comprehend." (PMID 23591077, 2013). "As observed with claudin 1, claudin 4 was also more prevalent in the cytoplasm of the tumor cells." (PMID 23721519, 2013). "Claudin-1 can function as a cancer-promoting and tumor suppressor factor depending on cancer type." (PMID 24009024, 2013). "However, in tumor lesions, claudin-1 exhibited dysregulated subcellular localization with moving away from its typical membranous position." (PMID 22408413, 2012). "On the other hand, major differences in CLDN1 expression were observed among tumours." (PMID 15743508, 2005). "The important issue is whether loss of CLDN1 and CLDN4 plays a significant role in cell–cell adhesion and tumour differentiation." (PMID 15743508, 2005). "Furthermore, the restoration of hsa-miR-375 levels might represent a therapeutic approach to mitigate these effects by repressing CLDN1 expression, potentially inhibiting tumor progression and improving patient outcomes." (PMID 40426863, 2025). "Thus, CCFM683 could prevent CRC by up-regulating MUC2, Claudin-1, and ZO-1, and promoting tumor cell apoptosis via the CLA-PPAR-γ axis." (PMID 39924893, 2025).
tumor (continued). "Taken together, these findings indicate that PABPC3 overexpression enhances metastatic capacity in vivo, with reduced expression of Claudin family members CLDN1 suggesting decreased tight junction integrity, which may be a potential reason for tumor metastasis." (PMID 41249135, 2025). "It seems that claudin-1/4 activity is tumor-specific and may change during progression." (PMID 39458944, 2024). "However, research has also shown that CLDN1 could exert tumor promoter characteristics by increasing the invasion or motility of cancer cells, which could decrease the efficacy of our cancer vaccine." (PMID 39309012, 2024). "Considering the critical role of the EMT process in tumor metastasis, we examined the expression of epithelial markers (E-cadherin and claudin-1) and mesenchymal markers (N-cadherin and vimentin) to address whether DDX17 is required for the EMT progression of CRC." (PMID 36593242, 2023). "Additionally, CLDN1 is remarkably hypomethylated in tumor samples of CRC." (PMID 35114976, 2022). "For E-cadherin, claudin-1, vimentin, and nuclear Snail/Slug expression, these differences occurred in both the tumor center and the tumor margin, whereas significantly higher levels in surgically resected samples were observed only at the tumor margin for ZEB1." (PMID 32093260, 2020). "In addition, we found that claudin-1 was related to the better tumor type (n = 6; RR, 0.60; 95% CI, 0.49–0.73; P < 0.00001), negative venous invasion (n = 4; RR, 0.81; 95% CI, 0.70–0.95; P = 0.001), and negative lymphatic invasion (n = 4; RR, 0.83; 95% CI, 0.74–0.92; P = 0.0009)." (PMID 32855635, 2020). "Indeed, we found that HDAC inhibitors could reactivate CLDN1 expression in tumor cells, and combined treatment with cisplatin and TSA or vorinostat had a synergistic cytotoxic effect." (PMID 32754286, 2020). "In addition, claudin-1 was associated with early tumor stage and negative lymph node metastasis, although not statistically significant (P = 0.09 and P = 0.10)." (PMID 32855635, 2020). "GAS6, AXL, and Cofilin-1 are overexpressed, but because of tissue-specific functions of claudins family, Claudin-1 may have a different role in various cancers; depending on the origin of cancer cells and the adjacent tumor microenvironment, it may increase or decrease in various cancers." (PMID 31700829, 2019). "Moreover, immunoblotting showed increased expression of the mesenchymal marker N-cadherin and decreased expression of claudin-1, a critical component of tight junctions and an epithelial marker, in UM-UC-5 cells treated with supernatants of tumour cell-platelet reactants." (PMID 28176852, 2017). "Moreover, CLDN1 nuclear localization in tumor samples was reported." (PMID 28659146, 2017). "Moreover, we found that the overexpression of CLDN1 could stimulate subcutaneous tumor growth and metastasis in athymic nude mice." (PMID 27974683, 2016). "However, other studies suggested that miR-155 may act as a tumor suppressor in certain solid tumors by targeting tumor oncogenes such as claudin-1 and c-Myc." (PMID 26934326, 2016). "We further test whether CLDN1-KD could inhibit tumor growth and metastasis in vivo." (PMID 25544763, 2015). "Thus, knockdown of CLDN1 suppressed tumor tumorigenesis in mice." (PMID 25544763, 2015). "Therefore we thought it important to assess whether tumors of the small intestine also progress with claudin-1 overexpression." (PMID 24997475, 2014). "CLDN1 expression and the covariates tumor size, positive lymph node fraction, histological type, gender and age at surgery were entered into a linear regression model, demonstrating that only CLDN1 and positive lymph node fraction were significant predictors of post-operative survival." (PMID 24321518, 2013).
tumor (continued). "The median percentage of tumor cells with membrane stain was 10%, whereas the median percentage of combined membrane and cytoplasmic staining was 30%, suggesting that a decrease in membrane staining resulted in an increase in cells in which claudin 1 was evident only in the cytoplasm." (PMID 23721519, 2013). "The anti-CD81 mAb 5A6 reversed the functions of CLDN1 overexpression in CRC malignant phenotypes and tumor xenograft growth." (PMID 42232600, 2026). "CLDN1-overexpressing SW620 cells and a xenograft tumor model were cotreated with the anti-CD81 monoclonal antibody (mAb) 5A6 to investigate the role of the CLDN1/CD81 axis in CRC tumor growth." (PMID 42232600, 2026). "In terms of tumor invasion, overexpression of miR-MTCO3P38 significantly increased E-cadherin and Claudin-1 expression and reduced N-cadherin level, while overexpression of TMOD1 reversed the situation." (PMID 39744479, 2025). "We performed scRNA-seq analysis on CLDN1, INHBA, and CXC12, regulated by both miRNAs and DNA methylation, in COAD tumor and normal colon tissue using GSE178341." (PMID 40426863, 2025). "Both CLDN1 (p = 2.94 × 10−133) and INHBA (p = 5.52 × 10−19) expressions were significantly up-regulated in a tumor progression-dependent manner." (PMID 40426863, 2025). "SPIOCA gavage fortified intestinal barrier integrity-evidenced by elevated ZO-1, ZO-2, Occludin and Claudin-1 expression-and potentiated antitumor immune-cell infiltration, specifically by CD8+ T cells and dendritic cells, into the tumor microenvironment." (PMID 41660285, 2025). "The results showed that the expression of IPCEF1, TFF3, GLT8D2, TPO and DIO1 were downregulated in the tumor group and DPP4, LRP4, CDH3, KCNJ2, CLDN1, GABRB2, FN1 were upregulated in the tumor group." (PMID 39513122, 2024). "The use of in vitro and in vivo models has demonstrated that targeting CLDN1, CLDN3, CLDN4, CLDN6 and CLDN18.2 consistently reduces tumor burden across a multitude of different cancer types, with specific intra-tumoral accumulation and low rates of AEs." (PMID 38371623, 2024). "A variety of protein partners can interact with CD81, either to regulate attachment and uptake of viruses (HCV E2, claudin-1, IFIM1) or to contribute to tumor growth and dissemination (CD19, CD44, EWI-2)." (PMID 37046846, 2023). "In this “one-two punch” approach, first oxaliplatin targets the bulk of tumor cells and then 6F6-ADC recognizes the residual resistant CLDN1-positive CRC cells." (PMID 37041570, 2023). "ThyroidPrint® is a novel q-PCR-based ten-gene classifier with its signature representing both the tumor microenvironment (CXCR3, CXCL10, CCR3, CCR7, and CXADR) and tumor epithelial cells (TIMP1, CLDN1, KTR19, AFAPL2, and HMOX1)." (PMID 37671897, 2023). "Patients whose tumours expressed claudin-1 were significantly less likely to achieve clinical remission following NAC and more likely to have residual tumours (χ2= 5, p= 0.025)." (PMID 37102018, 2023). "We found that between normal and tumor samples, CLDN8 and CLDN23 were downregulated and CLDN1 and CLDN2 were upregulated, respectively." (PMID 37799140, 2023). "In particular, claudin 1 was strongly expressed in the membranes and cytoplasm of the BCC cells mainly comprising the periphery of tumour nests." (PMID 36714681, 2023). "Our analyses of tumor samples collected from patients with CRC revealed a positive correlation between LIN28B, CLDN1, and NOTCH3 expression and CRC metastasis to the liver." (PMID 37318881, 2023). "As important markers in the tumor EMT process, E-cadherin, ZO-1, Claudin-1 decreased, N-cadherin and Vimentin increased in expression." (PMID 35509688, 2022). "Previous studies exploring the effects of CLDN1, CLDN2, CLDN4, CLDN11, CLDN12, CLDN14, and CLDN23 expression on CRC tumor growth have yielded findings consistent with our results in the present study." (PMID 35281827, 2022).
tumor (continued). "To validate these findings in vivo, we implanted control, CLDN1 and LCN2 depleted cells into the mammary fat pad of obese and lean mice and assessed tumor formation." (PMID 35013251, 2022). "Combined, these results suggest that CLDN1 and LCN2 are the downstream mediators of C/EBPB induced tumor formation capacity in the obese setting." (PMID 35013251, 2022). "The present study compares the expression of claudin-1, -2, -4, -5, and -7 in OSCC and in the healthy tissue of the same individual in 60 patients with tumor localization in different parts of the oral cavity." (PMID 36232536, 2022). "Methylated Solute Carrier Family 30 Member 10 (SLC30A10), claudin 1 CLDN1, and Inhibin Subunit Beta A (INHBA) were evidenced by SureSelectXT Methyl-Seq as being able to differentiate between normal and tumor tissue." (PMID 34638449, 2021). "CTTN overexpression (βadj. = 0.253, P < 0.05), CLDN-1 (βadj. = 0.345, P < 0.01), and CLDN-4 (βadj. = 0.338, P < 0.01) were significantly correlated to the larger tumor dimension in the models adjusted for potential covariates." (PMID 33407452, 2021). "The median relative expression of CLDN1 was 1.11 in paracancerous tissues and 1.91 in ESCC tissues, which was significantly increased in tumor tissues (Wilcox test, P = 0.042)." (PMID 34722771, 2021). "The overexpression of CTTN, CLDN-1, and CLDN-4 genes was correlated positively with the extent of tumor size." (PMID 33407452, 2021). "CLDN1 activates Src and PI3K by forming the CLDN1/Src complex, which increases tumor growth and liver metastasis in vivo by promoting EMT." (PMID 32456226, 2020). "CLDN-1 positively correlates with CRC cell proliferation and influences the growth and evolution of the tumor." (PMID 31952355, 2020). "ROC curves showed 75%, 75%, and 69% sensitivity and 88%, 81%, and 81% specificity for distinguishing neoplasia from normal for EGFR, claudin-1, and ErbB2, respectively." (PMID 36345439, 2020). "In this study, the expression levels of GAS6, AXL, Cofilin-1, Claudin-1, as genes involved in EMT, and their relationship with clinicopathological features include; age at diagnosis, TNM staging, size and grade of tumor were investigated in EOC patients." (PMID 31700829, 2019). "In the present case, tumor cells were positive for Glut-1/EMA and weakly positive for Claudin-1 on immunohistochemical staining." (PMID 30213264, 2018). "Immunohistologically, the tumor cells were positive for Glut-1, weakly positive for EMA, and weakly positive for Claudin-1, and the histopathological diagnosis was INPN." (PMID 30213264, 2018). "In comparison with the control group, except for miR-204-5p, the expression levels of ITGA2, FN1, ICAM1, CDH2, TIMP1, CLDN1, TNFRSF12A, miR-146b, and miR-222 were all up-regulated in the tumor group, consistent with the results of the bioinformatics analyses." (PMID 30414611, 2018). "Immunohistologically, the tumor cells were positive for Glut-1 and weakly positive for EMA and Claudin-1." (PMID 30213264, 2018). "We found that HCV RNA suppression in the tumor correlates with disruption of the typical linear distribution of two major HCV-entry cofactors, claudin-1 (CLDN1) and occludin (OCLN), which mediate viral entry into hepatocytes." (PMID 29538454, 2018). "We investigated in this study the expression of CLDNs- Claudin1 (CLDN1) and Claudin7 (CLDN7), and their relation to tumor progression in nasopharyngeal cancer (NPC)." (PMID 28055967, 2017). "The present study aimed to evaluate the expression of CLDN1 and CLDN7 under different cell differentiation status, and their relationship to tumor progression in NPCs." (PMID 28055967, 2017). "The protein expression levels of E-cadherin, N-cadherin, claudin-1, and vimentin were significantly higher in CLM than in primary tumor tissues (p < 0.05)." (PMID 27152521, 2016). "Our studies indicated that CLDN1 demonstrated oncogenic properties in both MDA-MB-231 and MCF7 cells, although it was a tumor suppressor in MDA-MB-361 cells." (PMID 26067567, 2015).
tumor (continued). "We also analyzed the expressions of Snail, E-cadherin, Claudin-1 and IL-8 as well as the phosphorylation levels of AKT and ERK1/2 in primary tumor tissues of mice formed by 1E8 control shRNA cells and P2X7 shRNA cells." (PMID 25486274, 2014). "CLDN1 and CLDN2 stained positive in 10–50% of tumor cells, while CLDN4 and CLDN7 stained positive in ≥50% of tumor cells." (PMID 25393310, 2014). "More specifically, knockdown of plakoglobin in MCF-7 cells resulted in the increased mRNA and protein levels of the tumor/metastasis promoters c-Abl, Snail, ErbB2 and MMP3 and the decreased levels of tumor/metastasis suppressors BRMS1, Kiss1 and Claudin-1." (PMID 24260116, 2013). "Recently, CLDN1 was successfully targeted with anti-CLDN1 near-infrared fluorophore to track the CRC cells, and it may provide a novel way for fluorescence-guided surgery of tumor." (PMID 41399659, 2026). "CLDN1 and INHBA are consistently over-expressed in COAD and are associated with poor prognosis and tumor progression, suggesting their potential role as negative prognostic biomarkers." (PMID 40426863, 2025). "Additionally, the TCGA database indicated significantly higher expression of CLDN1 and INHBA, while CXCL12 displayed lower expression between COAD tumor and control samples, consistent with our analysis results of the DEGs, DEMs, and DMRs." (PMID 40426863, 2025). "Therefore, a combination of IM and PDS-0330, a specific CLDN1 inhibitor, acted synergistically to induce apoptotic cell death and decrease the proliferative rate of GIST in vitro, and it effectively blocked tumor growth in the GIST xenograft model." (PMID 40943068, 2025). "Consequently, CLDN1 inhibition in GIST effectively disrupted the FGFR-mediated pathway and re-sensitized tumor cells to IM." (PMID 40943068, 2025). "Also, we verified that all the patients’ ascites EVs displayed EV-positive markers of CD63 and PDCD6IP (ALIX) proteins and tumour metastasis markers of N-cadherin (CDH2), claudin-1 (CLDN1) and angiogenin (ANG)." (PMID 40993350, 2025). "In contrast to claudin-1, meta-analysis suggests that MMP-1, MMP-2, MMP-9, and VEGF are highly expressed in RB, which are highly correlated with poor cell tumor differentiation, tumor invasion, and clinically advanced stage." (PMID 38920989, 2024). "Additionally, MMP2 upregulation can facilitate tumor cell invasion by breaking down the ECM, while Claudin-1 downregulation can disrupt cell–cell adhesion during the process of EMT." (PMID 38400838, 2024). "In ACC CLDN1 was the only marker that was negative in all tumor tissues, whereas in MEC there was no such a marker that was negative in all samples." (PMID 37621953, 2023). "Claudin-1 and β-catenin expressions within tumour cells shared several features including absent or weakness of membranous expression, and redistribution of both proteins to the cytoplasm of tumour cells, and in some cases to the nuclei of these cells." (PMID 37102018, 2023). "Furthermore, evidence of statistical and morphological correlation between claudin-1 and β-catenin expressions was presented, providing further indication about the role of claudin-1 in TNBC tumours." (PMID 37102018, 2023). "With the increasing grade of conventional MNSTs, we recorded a slight decrease in the expression of IHC markers Sox10, claudin-1, and GFAP, which could be the result of poorer differentiation of tumor cells in higher-grade tumors." (PMID 35622732, 2022). "Indeed, mRNA and protein expression levels of an epithelial gene (CLDN1) were decreased, while those of mesenchymal (VIM) and EMT regulator (Snail, Twist1, ZEB1, and ZEB2) genes were increased in tumor cells." (PMID 35618735, 2022). "Simultaneously, expression of TJ markers in tumor and normal squamous epithelial tissues revealed from both semiq-RTPCR and qPCR significant (p < 0.001) down regulation of ZO-1 (3.7-fold), CLDN-1 (2.9-fold), CLDN-7 (3.8-fold), OCLN (1.6-fold) and E-cadherin (2.3-fold) transcripts." (PMID 34316331, 2021).